PGRMC1 (progesterone receptor membrane component 1)
Diseases named in the same sentence as PGRMC1 in open-access papers (continued):
Sharing a sentence is not in itself a finding about the gene and the disease.
breast carcinoma (continued). "Moreover, numerous researches have shown that PGRMC1 is overexpressed in chemo‐resistant tumour cells, such as doxorubicin‐resistant and camptothecin‐resistant breast cancer cells, cisplatin‐resistant ovarian cancer cells and doxorubicin‐resistant uterine cancer cells." (PMID 32672400, 2020). "For this purpose, PGRMC1 was silenced using RNA interference, yielding similar results to those produced by AG-205, whereby decreased proliferation, increased apoptosis, cell-cycle arrest and inhibition of migration/invasion of breast cancer cells was observed." (PMID 32704174, 2020). "Additionally, higher expression of PGRMC1 may be useful in the prediction of prognosis of breast cancer patients." (PMID 33158280, 2020). "PGRMC1 may also function as an adaptor protein for multiple classes of steroid receptors, as PGRMC1 has been shown to transport mPRα and ERβ to the cell surface in a breast cancer cell line, but whether PGRMC1 acts as an adaptor protein in the brain is unknown." (PMID 28790975, 2017). "However, the findings related to PGRMC1 may help to elucidate the molecular mechanisms through which CYB5D1 reduced the malignant potency of breast cancer cells." (PMID 19851466, 2009). "Although we have demonstrated that PGRMC1 and σ2R/TMEM97 are involved in the same biochemical pathways within the cell, little is known about the impact of the individual components on breast cancer clinical outcomes." (PMID 39804138, 2025). "Note also that important genes distinguishing between cancer subtypes, e.g., for breast cancer, like ERBB2 (HER2), ESR1 (ER), and two forms of membrane component of PR, PGRMC1 and PGRMC2, survived shambhalization." (PMID 37745690, 2023). "For instance, EGFR is known to form complexes with PGRMC1, in a PGRMC1 dimer-dependent manner and both experimental strategies (siRNA and AG-205) led to reduced EGFR levels in breast cancer cells." (PMID 34680104, 2021). "High PGRMC1 expression was observed in 35 of 49 TNBC patients (71.14%), which is slightly higher than that we have been reported in breast cancer of all subtypes (69.60%, 48/69)." (PMID 34746100, 2021). "PGRMC1 was demonstrated to confer progestin responsiveness, which results in enhanced proliferation of MCF7 breast cancer cells in vitro and in vivo, indicating a potential role of PGRMC1 in increased breast cancer risk upon progestin-based HT." (PMID 34830790, 2021). "PGRMC1 has been reported to predict worse prognosis and correlate with MHT mediated signal transduction in breast cancer, whereas its involvement in TNBC remains poorly explored." (PMID 34746100, 2021). "Our experiments show that the decrease in the PGRMC1 protein leads to the suppression of metastasis in mice bearing breast cancer and migratory ability of MCF-7 and MDA-MB-231 breast cancer cells." (PMID 33832499, 2021). "As a part of this work, we assessed changes in protein modifications following PGRMC1 signal inhibition by AG-205 or PGRMC1 silencing in both ZR-75-1 and MDA-MB-468 breast cancer cell lines." (PMID 32704174, 2020). "Furthermore, our data demonstrate that PGRMC1 over-expressed in lung squamous cell carcinoma, kidney renal clear cell carcinoma, esophageal carcinoma and skin cutaneous melanoma, and plays an unfavorable prognosis role in head and neck cancer, breast cancer, acute myelocytic leukemia, and sarcoma." (PMID 31970154, 2019). "For instance, crosstalk between classical (ER and PR) and nonclassical (PGRMC1) signaling mechanisms exists in ER+ breast cancer cells, enhancing the growth of ER+/PR+/PGRMC1-overexpressing tumors." (PMID 40299687, 2025).
breast carcinoma (continued). "In summary, the present study shows that while whole-body knockout of Pgrmc1 was not sufficient for the suppression of growth of breast cancer, it significantly suppressed the degree of lung metastasis." (PMID 33832499, 2021). "It is important to determine whether breast cells overexpressing PGRMC1 are more likely to develop into tumor cells in women receiving E2/NET hormone therapy, which would help to determine the risks of MHT in relation to breast cancer." (PMID 34779589, 2021). "Our findings suggest the function of PGRMC1 as an important amplifier of ERα-dependent transcription upon treatment with the PPPs NET, DYD, DSP, and MPA, resulting in oncogenic signaling and tumor progression in ERα positive breast cancer cells." (PMID 34830790, 2021). "To identify responsible factors that are involved in oncogenic signaling of HR positive breast cancer cells, we performed Co-IP with HA-PGRMC1 followed by mass spectrometry and identified PHB1 and PHB2 as possible PGRMC1 interaction partners upon treatment with NET." (PMID 34830790, 2021). "In our study using the PyMT transgenic murine breast cancer model, genetic deletion of Pgrmc1 did not result in a significant difference in terms of cancer growth compared with WT mice." (PMID 33832499, 2021). "It is worth noting that in this study, 8 (ACTR3, ARF4, PGRMC1, RPS23, WDR12, ACTR2, SIAH1, and RPS27L) of 12 hub genes are related to cancers, such as lung cancer, epithelial ovarian cancer, gastric cancer, glioblastoma, breast cancer, and esophageal cancer." (PMID 33391181, 2020). "However, the role of membrane progesterone receptors (PGRMC1 and SERBP1), which are uniformly expressed across breast cancer cells, remains to be elucidated in these cells." (PMID 30337371, 2018). "Interestingly, we observed a widespread expression of membrane PRs (mPR, PGRMC1) in both PR-positive and PR-negative breast cancer cells, indicating that additional mechanisms could mediate progesterone functions." (PMID 37395734, 2023). "However, as the difference in the size of WT and Pgrmc1 KO tumors was not sufficient to show statistical significance, the development of breast cancer does not seem to be significantly affected by PGRMC1." (PMID 33832499, 2021). "In order to confirm that the negative effect of P4 on breast cancer cells course by activation of PGRMC1, we analyzed the number of dead cells by using the PI uptake protocol in MDA-MB-231 cells that were previously transfected with the scramble or shPGRMC1 plasmids." (PMID 33076541, 2020). "On Western blots of breast cancer whole cell proteins, that antibody generated a low background smear of signals across many molecular weights, in addition to recognizing exogenously expressed PGRMC1 but not a S181A mutant (not shown)." (PMID 32293262, 2020). "Furthermore, PGRMC1 was shown to be differentially phosphorylated between estrogen receptor-positive and negative breast cancers." (PMID 32293262, 2020). "Furthermore, the heme-binding defective mutant, PGRMC1(D120G), reduced the survival of MDA-MB-231 breast cancer cells from doxorubicin and camptothecin, implicating the heme-binding capacity of PGRMC1 in regulating susceptibility towards chemotherapeutic agents." (PMID 24466094, 2014). "PGRMC1 was previously reported to be more abundant in a variety of cancers, including breast cancer (although differential ER-α status was not reported), and a perinuclear localization was suggested to implicate it in a role involving cytochrome P450 activation and steroid metabolism." (PMID 18922159, 2008). "Interestingly, AG-205 did not decrease PGRMC1 expression in breast cancer cells, as in our study." (PMID 39464509, 2024). "A differential PGRMC1 phosphorylation status was shown between estrogen receptor-positive (ER+) and negative (ER-) breast cancers (BC), an indication that PGRMC1 may be involved in the clinical differences between tumors with distinct ER statuses, in a phosphorylation-dependent manner." (PMID 38804287, 2024).
breast carcinoma (continued). "However, PGRMC1’s role in tumor development and progression is not limited to breast cancer." (PMID 34831222, 2021). "Despite its lack of specificity towards PGRMC1, AG-205 may remain attractive for its anti-mitotic, anti-migratory and anti-invasive activities which stimulated hopes of therapeutic applications, as illustrated by the patent targeting breast cancer." (PMID 34680104, 2021). "Therefore, it can be speculated that PGRMC1 promotes the metastatic phenotype in breast cancer cells regardless of the interference hormone receptors." (PMID 33832499, 2021). "In a proteomics project, differential PGRMC1 phosphorylation in estrogen receptor-positive and -negative breast cancer has been observed, indicating that not only the expression level but also PGRMC1's phosphorylation may play a role in breast cancer." (PMID 29069804, 2017). "Interestingly, these results are opposite to those reported for PGRMC1 which has been shown to promote MDA-MB-468 breast cancer cell growth in the presence and absence of serum, while the heme-binding defective PGRMC1(D120G) mutant inhibited cell proliferation." (PMID 24466094, 2014).
ovarian carcinoma (28 papers, 2011 to 2025). A malignant neoplasm originating from the surface ovarian epithelium. "PGRMC1 exhibits high expression levels in breast and ovarian cancer tissues, where it is closely associated with malignant biological behaviors, including tumor cell proliferation, migration, and invasion." (PMID 41153737, 2025). "The prognostic impact of PGRMC1 is largely unexplored in ovarian cancer, but high serum-levels of relaxin-2 have been associated with tumor progression and adverse survival in several malignancies, including ovarian cancer." (PMID 38578428, 2024). "Since PGR is only expressed in about 50% of endometrial cancers, the loss of PGR could lead to an increase in PGRMC1 as suggested for ovarian cancer." (PMID 34885064, 2021). "If so, then the progressive decrease in PGR that is associated with the increasing stage of the ovarian cancer could account for the corresponding increase in PGRMC1 expression." (PMID 34885064, 2021). "Progesterone exhibits anti-apoptotic activity in ovarian cancer, but cells depleted of PGRMC1 showed increased apoptosis when treated with progesterone." (PMID 39502961, 2024). "It was demonstrated that miR-98, alongside let-7, targets and regulates PGRMC1 expression, a component known to be tied to chemoresistance, suggesting a regulatory mechanism for PGRMC1 expression in ovarian cancer." (PMID 38872210, 2024). "The PGRMC1 (Membrane-associated progesterone receptor component 1) is known to be involved in ovarian cancer as well as PTGIS (Prostacyclin synthase) and the Protein NDRG1 known to modulate genes involved in ovarian cancer metastasis." (PMID 37775701, 2023). "A significantly up-regulated expression of PGRMC1 in advanced human ovarian cancers has been suggested to indicate its important role in disease progression." (PMID 37894441, 2023). "Why ablating PGRMC1 renders ovarian cancer resistant to chemotherapy while enhancing the sensitivity of endometrial cancers remains to be determined." (PMID 34885064, 2021). "Treatment with the Let-7 mimic suppressed PGRMC1 mRNA levels in the ovarian cancer cell line, SKOV-3." (PMID 34885064, 2021). "To date, there has been only one xenograft model developed to assess PGRMC1′s role in ovarian cancer." (PMID 34885064, 2021). "PGRMC1/Sigma-2 receptor is confirmed to play key roles in the function of tumor proliferation (such as breast tumors, lung adenocarcinoma cells, and ovarian cancer) and chemoresistance." (PMID 33391181, 2020). "It has been reported that PGRMC2 interacts with PGRMC1 as a heterodimer in an exogenous expression system in human ovarian carcinoma cells, but homodimerisation of PGRMC2 has not been shown yet." (PMID 27754849, 2016). "This is, to our knowledge, the first report of PGRMC1 expression in a relatively large cohort of ovarian cancers." (PMID 27867772, 2015). "For instance, PGRMC1 expression increases while cognate, nuclear PR decreases in advanced stages of ovarian cancer, and overexpression of PGRMC1 interferes with the lethality of cisplatin, suggesting a survival role for PGRMC1 in ovarian cancer development." (PMID 21619605, 2011). "Similarly, in ovarian cancer, PGRMC1 enhances cell proliferation and migration through the activation of the ERK1/2 signaling pathway." (PMID 41153737, 2025). "This protective effect of progesterone may be partly due to the PGR-mediated suppression of progesterone receptor membrane component-1, which enhances the sensitivity of ovarian cancer cells to platinum-based chemotherapy." (PMID 37569592, 2023). "Our present observations on the P4 receptor expression pattern in CRC are consistent with the recently reported marginal expression of PGR, with low expression levels of mPRβ, mPRγ, and PGRMC2, and abundant expression levels of PGRMC1 in high-grade human ovarian cancer." (PMID 37894441, 2023). "PGRMC1 (progesterone receptor membrane component 1) is overexpressed in ovarian cancer cells." (PMID 35498135, 2022).
ovarian carcinoma (continued). "Moreover, the latest research has found that PGRMC1 induces autophagy through directly binding with light chain 3 beta 2 (LC3B2), and hyperoside can sensitize ovarian cancer cells to cisplatin by activating PGRMC1-dependent autophagy." (PMID 35152910, 2022). "In addition, the expression of PGR decreases and PGRMC1 increases with ovarian cancer progression and as a result the ratio of PGRMC1 to PGR dramatically increases with the stage of ovarian cancer." (PMID 34885064, 2021). "As Let-7i is down regulated in ovarian cancer, the decrease in Let-7i expression in ovarian cancer could be part of the mechanism that accounts for an increase in PGRMC1 expression." (PMID 34885064, 2021). "In human ovarian cancers, abundant PGRMC1 expression level has also been demonstrated." (PMID 33158280, 2020). "Moreover, we showed MF treatment of ovarian cancer was ineffective due to its agonistic PGRMC1 action that enhanced the tumor growth." (PMID 33158280, 2020). "Thus, the finding that high PGRMC1-expressing tumors correlate with poor overall survival emphasizes the importance of PGRMC1 as a therapeutic target in ovarian cancer." (PMID 27867772, 2015). "PGRMC1 was highly expressed in lung and ovarian cancers and correlated with patient survival." (PMID 27867772, 2015). "Additionally, studies reveal that PGRMC1 is overexpressed in ovarian cancer." (PMID 40098612, 2025). "Moreover, PGRMC1 has been involved in ovarian cancer cell invasion." (PMID 33158280, 2020). "As with PGRMC1, PGRMC2 is elevated in ovarian cancer and a large number of ovarian cancer cell lines." (PMID 40227710, 2025). "Previous studies have demonstrated that in an ovarian cancer cell line, SKOV-3 cells, PGRMC1, and PGRMC2 interact with tubulin to regulate the stability of the mitotic spindle." (PMID 34885064, 2021). "Not only are PGRMC1 and PGRMC2 expressed in ovarian cancer, but the nuclear progesterone receptor (PGR) is also expressed." (PMID 34885064, 2021). "The relationship between the expression profile of PGRMC1 and PGRMC2 and ovarian cancer is complex because expression and cellular location vary with the subtype of ovarian cancer and the stage of progression." (PMID 34885064, 2021). "Researchers have demonstrated that hyperoside can induce apoptosis in ovarian cancer cell lines HO-8910 and SKOV3 through the progesterone receptor membrane component 1 (PGRMC1)-dependent autophagy pathway, while also enhancing the cells’ sensitivity to the chemotherapy drug cisplatin." (PMID 40098612, 2025). "Progesterone’s protective effect may be attributed to PGR’s suppression of progesterone receptor membrane component-1 (PGRMC1), which increases the sensitivity of ovarian cancer cells to platinum-based chemotherapy." (PMID 37569592, 2023). "These genes encode proteins that function as intracellular chaperones and could direct the subcellular distribution of PGRMC1 and PGRMC2 and likely contribute to ovarian cancer progression." (PMID 34885064, 2021). "Although endometrial cancer stem cells have not been examined, ovarian cancer stem cells express PGRMC1, which also stimulates stem cell self-renewal." (PMID 34885064, 2021). "Interestingly, in the ovarian cancer cell line, SKOV-3, P4 increased the levels of Let-7 and decreased the levels of PGRMC1 mRNA." (PMID 34885064, 2021). "The use of mifepristone for breast and ovarian cancer, while suppressing the PIBF protein, may also negate the role that the nPR plays in inhibiting possibly some other protein, e.g., hypothetically, PGRMC-1, that promotes tumor proliferation." (PMID 34830233, 2021). "Whether the abilities of PGRMC1 and PGRMC2 to influence the composition of the ribosomes and thereby which RNAs get translated into specific proteins changes at different stages of ovarian cancer remains to be determined." (PMID 34885064, 2021).
ovarian carcinoma (continued). "PGRMC1 originally was identified by expression induction during carcinogenesis in liver cancer, and recently was observed its elevation with tumor stage in ovarian cancer and estrogen receptor-negative breast cancer." (PMID 31970154, 2019). "Similarly depleting PGRMC2 but not PGRMC1 also increases ovarian cancer cell migration." (PMID 34885064, 2021).